PGR (progesterone receptor)
Diseases named in the same sentence as PGR in open-access papers (continued):
Sharing a sentence is not in itself a finding about the gene and the disease.
tumor (continued). "This study’s findings suggest that tumor size and tumor grade is associated with long-term survival, and patients with larger tumors, lower tumor grades, and progesterone receptor–positive status experienced significant treatment benefit with receipt of tamoxifen therapy." (PMID 34190995, 2021). "Identification of the mechanism of PgR loss in each patient seems challenging, yet it may provide important information on the biology of the tumor and predict its responsiveness to the therapy." (PMID 34638241, 2021). "However, under pathological conditions, ESR1, ESR2, and PGR have been demonstrated to be associated with tumorigenesis and tumor progression." (PMID 34322374, 2021). "Therapies are selected based on the biological characteristics of the tumor, namely subtypes classified by the expression of estrogen receptor alpha (ER), progesterone receptor (PR), and amplification of the gene encoding the human epidermal growth factor receptor 2 (HER2)." (PMID 34736512, 2021). "Genetic mutations can lead to BC and have been experimentally linked to some tumor markers, including progesterone receptor (PR), estrogen receptor (ER), and human epidermal growth factor receptor type 2 (HER2) statuses, which are used clinically in the classification of BC." (PMID 31979384, 2020). "Ligand-activated PGR has been implicated as a tumor suppressor in EC." (PMID 32046384, 2020). "In the subgroup analysis, we found no statistical evidence that the effect of the treatment type was significantly associated with age, tumour size, lymph node status, oestrogen and progesterone receptor status, proliferative rate, tumour grade or menopausal status." (PMID 32231293, 2020). "In addition, NEDD4-positive staining was associated with clinical parameters, including tumor size (P = 0.030), nodal status (P = 0.001), estrogen receptor status (P = 0.035), and progesterone receptor status (P = 0.023)." (PMID 31856858, 2019). "Finally, we found by multivariate survival analysis that cancer-specific survival depended on the proposed histological stages, i.e., cancer spread within patients, as well as Progesterone Receptor positivity, and tumor-associated inflammation." (PMID 31788484, 2019). "In the discovery cohort, low cytoplasmic DARPP-32 expression was significantly associated with ER and PgR positive tumours (χ2 = 25.893, d.f. = 1, P < 0.001 and χ2 = 7.384, d.f. = 1, P = 0.007 respectively) and absence of triple negative disease (χ2 = 10.607, d.f. = 1, P = 0.001)." (PMID 31740718, 2019). "It remains unclear if tumor expression of estrogen receptor (ER) or progesterone receptor (PR) is independently associated with EC survival after adjusting for histologic type and tumor grade." (PMID 28476021, 2017). "In addition to the association with survival of these patients, high calpastatin expression is associated with ER positive tumours and high calpain-1 expression is associated with PgR positive tumours." (PMID 27323818, 2016). "The main finding of this study was that moderate/strong HMGCR expression was significantly associated with several indolent tumor characteristics, including lower histological grade, ER and PgR positivity, HER2 negativity, and less axillary lymph node involvement." (PMID 26109908, 2015). "Sie at al. examined whether tumor expressions of the progesterone receptor (PR) and estrogen receptor (ER) were associated with subtype-specific survival." (PMID 26576867, 2015). "Furthermore, the gene encoding PgR is located at the proximal part of the 11q chromosomal arm, which is commonly deleted in 11q13/8p12 amplified tumours." (PMID 24131622, 2013).
tumor (continued). "The association of the T variant with tumor PgR-positivity, which was per se a favorable prognostic factor for survival in this study, may have accounted for the observed better patient outcome." (PMID 23935969, 2013). "A strong correlation was found between the percentage of CD44+/CD24− cells in primary tumours and distant metastasis development (p = 0.0001); in addition, there was an inverse significant association with ER and PGR status (p = 0.002 and p = 0.001, respectively)." (PMID 23028444, 2012). "In addition, progesterone receptor status (p = 0.0190, HR = 2.7, 95% CI 1.2 - 6.0) was significantly associated with time-to-distant metastasis in this group whereas tumor stage, endocrine treatment, tumor grade, and age at surgery were not." (PMID 20515469, 2010). "However, perhaps due to the relative small sample of tumors analyzed, we were unable to detect any associations between leptin/ObR and either tumor grade, ERα/PgR, or metastasis, reported by different authors previously." (PMID 18945363, 2008). "No other statistically significant associations between ER isoforms and established prognostic variables such as tumour size, age at diagnosis, node status, inflammation or progesterone receptor, were observed (showing associations with cut-points equivalent to the 25th percentile)." (PMID 16880783, 2006). "Furthermore, when ER- and PgR – tumours were considered together the association was stronger (p = 0.003)." (PMID 15904529, 2005). "However, anastrozole treatment caused a marked reduction in expression of PgR in 17 of the 18 receptor-positive tumours (in 11 cases this was a total loss)." (PMID 12177804, 2002). "Therefore, any alteration in the biological function of PGR due to polymorphisms may alter the progesterone-mediated tumor suppression, thereby increasing EC risk." (PMID 36981012, 2023). "The complete mechanisms underlying LGSOC development are still not fully understood; however, the abundant expression of sex hormone receptors in LGSOCs suggests that estrogen receptor (ER) and progesterone receptor (PR) expression patterns may be associated with both tumor activity and prognosis." (PMID 35735430, 2022). "Meta-analyses and systematic reviews have shown that numerous factors—including age, genetic polymorphisms, tumor-infiltrating lymphocytes, programmed death-ligand 1, ER, progesterone receptor, and HER2 expression status—may be predictive of response to NAC in women with breast cancer." (PMID 34282214, 2021). "By siRNA targeting of KLF9 in Ishikawa cells to mimic the low levels found in EC tumors, we found that MET may compensate for the progressive loss of KLF9 in tumor cells by rapidly increasing transcript levels for PGR, PGR-B, and KLF4, all of which exhibit anti-tumor properties." (PMID 32046384, 2020). "Although both AP-2α and AP-2α/β specific antibodies detected tumours with a significant association with ER, the association was stronger when using the AP-2α/β marker as indicated by the strong association with the hormonal receptor PgR and luminal marker CK19." (PMID 20025767, 2009). "In the present material, positive ER, PgR or HER2 expression in primary tumor, and positive ER or HER2 expression in liver metastasis were beneficial for overall survival compared to those with negative receptors." (PMID 41511682, 2026). "Medical records were reviewed for patient demographics, tumour characteristics, and receptor status (estrogen receptor, progesterone receptor, and HER2)." (PMID 41495862, 2026). "Positive PgR in the primary tumor was also related to enhanced survival (p = 0.002), although, PgR status in the metastases did not (p = 0.367)." (PMID 41511682, 2026).
tumor (continued). "Further, that positive PgR in the primary tumor and positive ER in both primary tumor and liver metastasis are favourable prognostic biomarkers." (PMID 41511682, 2026). "Immunohistochemical staining results indicated that the tumor cells were positive for estrogen receptor (ER) (80%, 2+) and progesterone receptor (PR) (60%, 2+)." (PMID 40994809, 2025). "Regarding tumor subtypes, 64.4% were ER-positive, 41.4% were PgR-positive, and 23.3% were HER2-positive." (PMID 41194812, 2025). "While both our patients demonstrated hormone receptor status consistent with that of the primary tumor (ER+, PgR+, and HER2–), previous studies have shown substantial discordance rates." (PMID 41536970, 2025). "Since the immunohistochemical expression of ER and PgR was positive, relugolix (40 mg/day) was orally administered daily for six months, resulting in significant tumor regression (8.7 cm to 4.6 cm)." (PMID 40291187, 2025). "In this prospective study, we evaluated the effectiveness of NET with letrozole and explored early changes in tumor biology, including the proliferation marker Ki-67 and progesterone receptor (PgR) expression." (PMID 40723203, 2025). "The keywords are divided into three major clusters: Cluster 1 (red nodes, Target Therapy/Checkpoint Inhibitors), Cluster 2 (green nodes, Tumor Immune Microenvironment/Immune Infiltration), and Cluster 3 (blue nodes, Estrogen/Progesterone Receptor)." (PMID 40264788, 2025). "Tumor stage, estrogen receptor (ER) status, and progesterone receptor (PR) status were more frequently reported, appearing in three studies." (PMID 40061142, 2025). "Hormone receptors, specifically the estrogen receptor (ER) and progesterone receptor (PR), as well as human epidermal growth factor receptor-2 (Her2), are tumor-specific markers used to guide breast cancer therapy." (PMID 41155845, 2025). "Estrogen/Progesterone receptor (ER/PR)-positive tumor was lower in the LRT group (84% vs. 89%, p = 0.04), although hormonal therapy was administered equally (85% in both groups, p = 0.99)." (PMID 41149476, 2025). "These molecular subtypes can be approached by measuring four tumor markers: estrogen receptor (ER), progesterone receptor (PgR), HER2, and Ki67." (PMID 39902259, 2025). "In our study, among the considered pathological parameters, tumor grading, Ki67, ER, and PgR displayed a significant correlation with RS, with some differences according to menopausal status." (PMID 40717834, 2025). "Using the structured dataset, we found that patients exhibiting both very low progesterone receptor (PR) levels and very high tumor cell growth (Ki-67 ≥ 40%) had significantly worse outcomes than other luminal breast cancers." (PMID 41375036, 2025). "Prognosis is significantly influenced by well-established clinicopathological factors, such as nodal status, tumor grade, Ki-67 proliferation index, and progesterone receptor expression on immunohistochemistry (IHC)." (PMID 41375036, 2025). "Low proliferation was associated with a decreased risk for RFI events in the univariable analysis (HR = 0.23, 95 %CI: 0.06–0.82) and HR = 0.05, (95 %CI: 0.01–0.42) after adjusting for baseline PgR status, tumor size, and age." (PMID 41242143, 2025). "SPF has been correlated with nuclear grade, tumor size, estrogen receptor, progesterone receptor, metastasis, and clinical response to neoadjuvant chemotherapy." (PMID 40519486, 2025). "The fact that ER and PgR were positive in this case also suggests an endocrine-dependent nature of the tumor." (PMID 40144425, 2025). "The tumor maintained its previous biomolecular characteristics: ER and PgR negativity, HER2 3+ positivity, and Ki-67 35%." (PMID 40843868, 2025). "For estrogen receptor (ER)-positive and/or progesterone receptor (PR)-positive tumors, hormone therapy is the main treatment, with chemotherapy incorporated according to tumor size, grade, and lymph node status." (PMID 40591167, 2025).
tumor (continued). "After adjusting for the baseline covariates PgR status, tumor size, and age, the results for C2 and surgery were HR = 1.45, (95 %CI: 0.13–16.10) and HR = 0.06, (95 %CI: 0.01–0.50), respectively." (PMID 41242143, 2025). "Using IHC, low Ki67 (<10 %) was associated with a reduced risk of recurrence, with a HR of 0.88 (95 %CI: 0.38–2.04) and a corresponding HR of 0.71 (95 %CI: 0.26–1.94) after adjusting for baseline PgR status, tumor size, and age." (PMID 41242143, 2025). "Positive immunohistochemical staining for ER and PgR and the age of onset suggest a relationship with sex hormones, and hormone therapy can reduce tumor size." (PMID 40291187, 2025). "Hormone receptor (estrogen receptor (ER) and progesterone receptor (PR))-positive luminal tumours, accounting for 70-80% of all BCa, are treated with hormone therapy but still a proportion recurs." (PMID 41310336, 2025). "Most significant features associated with race include Lymphadenopathy_or_Suspicious_Nodes, Estrogen Receptor status (ER), Molecular Subtype, Tumor Grade Mitotic and Nuclear, and Progesterone Receptor status (PR)." (PMID 40941009, 2025). "The disease is classified based on histological grading, tumor stage, and the expression of key biomarkers such as estrogen receptor (ER), progesterone receptor (PR), and human epidermal growth factor receptor 2 (HER2)." (PMID 40699776, 2025). "Tumor evolution, therapeutic intervention, or heterogeneity of the tumor microenvironment can alter ER, PgR, or HER2 status." (PMID 41209903, 2025). "Pathological examination revealed a multifocal tumor continuous with the pancreatic parenchyma, showing mucous epithelium and progesterone receptor (PgR)-positive OTS." (PMID 40008371, 2025). "The tumor was estrogen receptor (ER)-positive, progesterone receptor (PR)-positive, human epidermal growth factor receptor 2 (HER2)-low, with a Ki-67 proliferation index of 25%." (PMID 41510417, 2025). "Independent prognostic value was demonstrated by controlling clinical and demographic variables such as age, tumor grade, stage, ER status, progesterone receptor status, and human epidermal growth factor receptor 2 status." (PMID 41091832, 2025). "Factors like tumor grade, Ki67 levels, and progesterone receptor status can help to select patients who are more likely to benefit from NACT than NET." (PMID 40647384, 2025). "Immunohistochemical staining showed that the tumor cells were positive for desmin, smooth muscle actin, estrogen receptor, and progesterone receptor and focally positive for PAX8." (PMID 39676599, 2025). "Immunohistochemical analysis confirmed the tumour’s negativity for estrogen receptor and progesterone receptor, ruling out metastatic spread from a uterine source and establishing this as a primary malignancy." (PMID 40433213, 2025). "This trend persisted after adjusting for baseline PgR status, tumor size, and age (SSP-Ki67: HR = 0.38, 95 % CI: 0.03–4.15), although non-significant, likely due to the small number of cases included in the analysis." (PMID 41242143, 2025). "At the time of diagnosis, the tissue of the tumor was investigated for the rate of tumor cell growth (ki-67 labeling index, primary endpoint), c-erB2 expression, apoptosis, and estrogen & progesterone receptor levels." (PMID 40612872, 2025). "ASCO/CAP guidelines recommend defining ER-low positivity as if 1–10% of tumor cell nuclei are immunoreactive for ER and suggest that similar principles apply to PgR testing, which is used primarily for prognostic purposes in the setting of ER-positive BC." (PMID 40002286, 2025). "Conversely, GSN and PGR exhibited lower protein expression in tumor tissues relative to normal tissues, aligning with their favorable prognostic roles and reduced expression in the high-risk group." (PMID 41244925, 2025).
tumor (continued). "In contrast, the reduced expression of GSN and PGR in tumor tissues supports their role as favorable prognostic markers, potentially through impaired cell adhesion and hormone response, respectively." (PMID 41244925, 2025). "The PCNA immunostaining revealed that Capan-1 cells bearing PGR shRNA showed inhibition of PDAC tumor progression." (PMID 38424455, 2024). "The tumor cells expressed estrogen receptor (ER) at 60%, progesterone receptor (PR) at 5%, and androgen receptor (AR) at 80%, a Her-2/neu score of 1+ and negative for CK5/6." (PMID 38611678, 2024). "Treatment decisions in BC rely primarily on tumor molecular subtypes, which depend on the expression of the estrogen receptor, progesterone receptor, and HER2 receptor." (PMID 38379328, 2024). "Other investigated factors include patient age and sex, tumor size, location and morphology, brain invasion, progesterone receptor (PR) expression." (PMID 38656725, 2024). "For all samples, Haematoxylin‐and‐Eosin (H&E) staining as well as Immunohistochemistry (IHC) for ERα were performed to enable assessment of tumour percentage (ranging between 35% and 90% in all samples) and status of ERα, progesterone receptor (PR) and HER2." (PMID 37854018, 2024). "Tumour SUVmax was lower in T1 than T2 tumour size (p=0.027) and progesterone receptor-positive patients (p=0.029)." (PMID 38164229, 2024). "TNBC is a heterogenous tumor where the cancer cells lack estrogen receptor (ER), progesterone receptor (PR), and human epidermal growth factor receptor 2 gene (HER2) amplification." (PMID 38633889, 2024). "The immunohistochemical examination revealed the presence of the nuclear progesterone receptor (PGR) in the tumor tissue." (PMID 38715073, 2024). "The distribution of the tumor characteristics estrogen receptor, progesterone receptor, human epidermal growth factor receptor 2, and histological subtypes were similar in Group A–C, whereas highly proliferative tumors (Ki67) were more common in Group A." (PMID 39129250, 2024). "In U87MG-luc-R and A172-luc cells, PgR overexpression improved NK-92-mediated tumor killing, and Abi + Prog treatment further enhanced this effect." (PMID 39103871, 2024). "For instance, tumor size correlated negatively with NK cell mobilization at E15, and progesterone receptor positivity correlated negatively with CD8+ T-cell mobilization." (PMID 38979417, 2024). "Statistically significant interactions between tumour characteristics and age were found (p < 0.05) except for ER and PgR." (PMID 38454634, 2024). "Several studies incorporated clinicopathological features directly related to BC, including age, cancer stage, grade, tumor size, estrogen receptor (ER) status, progesterone receptor (PR) status, and human epidermal growth factor receptor 2 (HER2) status." (PMID 39839787, 2024). "When it comes to treatment considerations for breast cancer, several factors are taken into account, including the expression of HER2, progesterone receptor (PR), and estrogen receptor (ER), along with other patient- and tumor-specific characteristics." (PMID 38726321, 2024). "Histopathological markers related to proliferation of tumor cells were determined (Her‐2‐neu, Ki‐67, estrogen receptor, and progesterone receptor)." (PMID 38389406, 2024). "The tumor was characterized as ER+ at 92%, progesterone receptor positive (PR+) at 63%, and human epidermal growth factor receptor 2 (HER2)/neu negative, with a high proliferation index (Ki-67 of 92%)." (PMID 39553033, 2024). "Established biomarkers such as HER2, estrogen receptor (ER), and progesterone receptor (PR) status provide valuable insights into tumor biology and response to therapy." (PMID 39359789, 2024).